ANKRD17 (ankyrin repeat domain 17)
Description:
Could play pivotal roles in cell cycle and DNA regulation. Involved in innate immune defense against viruse by positively regulating the viral dsRNA receptors DDX58 and IFIH1 signaling pathways. Involves in NOD2- and NOD1-mediated responses to bacteria suggesting a role in innate antibacterial immune pathways too. Target of enterovirus 71 which is the major etiological agent of HFMD (hand, foot and mouth disease). Could play a central role for the formation and/or maintenance of the blood vessels of the circulation system (By similarity).
Synonyms: GTAR; KIAA0697; FLJ22206; NY-BR-16; MASK2; CAGS
Tractability: PROTAC: UniProt records ubiquitination sites on it; ubiquitination databases record sites on it; its protein half-life has been measured.
Gene: Protein-coding gene on chromosome 4 (73,073,376 to 73,259,147, reverse strand). Ensembl gene ENSG00000132466.
Subcellular location: Cytoplasm; Nucleus
Subcellular location (Human Protein Atlas): Nucleoplasm; Nuclear membrane
Gene Ontology:
Molecular function: chromatin binding; protein binding; RNA binding; nucleic acid binding
Biological process: defense response to bacterium; innate immune response; positive regulation of canonical NF-kappaB signal transduction; positive regulation of cell cycle; positive regulation of G1/S transition of mitotic cell cycle; positive regulation of MDA-5 signaling pathway; positive regulation of RIG-I signaling pathway; regulation of DNA replication
Cellular component: chromatin; cytoplasm; membrane; nucleoplasm; nucleus
Genetic constraint (gnomAD): Loss-of-function variants: 17 observed, 216.18 expected, observed/expected ratio (o/e) 0.0786, 90% interval 0.053 to 0.12. The upper end of that interval is the gene's LOEUF score, 0.12, which puts it in group 1 of 6, group 1 being the genes least tolerant of losing a copy. Missense variants: 2,160 observed, 3,255.8 expected, observed/expected ratio (o/e) 0.66, 90% interval 0.64 to 0.69. Synonymous variants: 1,109 observed, 1,175.6 expected, observed/expected ratio (o/e) 0.94, 90% interval 0.9 to 0.99.
Gene-disease validity (ClinGen):
ClinGen rates the evidence that ANKRD17 causes each of these diseases.
syndromic complex neurodevelopmental disorder (autosomal dominant): Definitive. A disorder that involves more than one phenotype associated with the central nervous system, including but not limited to intellectual disability, autism, and seizures (epilepsy), and also a distinctive pattern of other features including dysmorphisms and/or congenital malformations.
Homologues: Orthologues: chimpanzee ANKRD17 (99% identical), macaque ANKRD17 (99% identical), pig ANKRD17 (99% identical), rat Ankrd17 (97% identical), dog ANKRD17 (94% identical), rabbit ANKRD17 (93% identical), mouse Ankrd17 (93% identical), guinea pig ANKRD17 (92% identical), tropical clawed frog ankrd17 (84% identical). Paralogues in human: ANKHD1 (60% identical).
Diseases named in the same sentence as ANKRD17 in open-access papers:
ANKRD17 is named in the same sentence as 22 diseases in open-access papers, as found by Europe PMC text mining. Sharing a sentence is not in itself a finding about the gene and the disease. The quoted sentences say what the papers report.
breast carcinoma (4 papers, 2008 to 2021). "Clone Pr48 is similar to the gene encoding human ankyrin repeat domain 17, which has also been isolated from breast cancer (NY-BR-16, Genbank accession number AF308285)." (PMID 18949081, 2008).
Chopra-Amiel-Gordon syndrome (2 papers, 2022 to 2024). "The Ankyrin Repeat Domain Containing Protein 17 (ANKRD17, OMIM:615929) gene is a protein-coding gene associated with diseases such as Chopra-Amiel-Gordon Syndrome and Non-Specific Syndromic Intellectual Disability." (PMID 39315309, 2024).
glioma (2 papers, 2022 to 2024). A benign or malignant brain and spinal cord tumor that arises from glial cells (astrocytes, oligodendrocytes, ependymal cells). "In addition, low expression of WASF2 in glioma was correlated with increased survival rate, whereas the ANKRD17 expression was suggested to have little effect on the survival rate of patients." (PMID 35849030, 2022). "In glioma, PTBP1 bound to the pre-mRNA of ANKRD17 to promote circANKRD17 expression." (PMID 38993556, 2024). "The expression of ANKRD17 and WASF2 in glioma was predicted in the GEPIA system." (PMID 35849030, 2022). "WASF2 was suggested to be highly expressed in glioma, whereas the ANKRD17 expression was not significantly changed in glioma tissues compared to normal tissues." (PMID 35849030, 2022).
Intellectual disability (2 papers, 2020 to 2025). "Ankyrin repeat domain 17 (ANKRD17) is a gene implicated in intellectual disability (ID) and autism spectrum disorder (ASD)." (PMID 40604385, 2025). "ANKRD17 has recently been implicated in intellectual disability (ID) and autism spectrum disorder (ASD); however, the underlying molecular mechanisms remain unclear." (PMID 40604385, 2025). "We highlight ADAMTS3, ANKRD17 and RNU4ATAC9P as candidate genes for intellectual disability, growth retardation and congenital heart defect." (PMID 32299451, 2020).
Anxiety (1 paper, 2025). Intense feelings of nervousness, tension, or panic often arise in response to interpersonal stresses. "This study integrates clinical cases with knockdown mouse models to confirm the association between ANKRD17 deficiency and autism, anxiety, and spatial memory impairments." (PMID 40604385, 2025). "By integrating clinical cases with knockdown mouse models, we demonstrate that ANKRD17 haploinsufficiency is associated with deficits in social behavior and increased anxiety." (PMID 40604385, 2025). "We then conducted an open field test to evaluate the anxiety levels of mPFC control and Ankrd17-knockdown mice." (PMID 40604385, 2025).
Cerebellar hypoplasia (1 paper, 2025). Cerebellar hypoplasia is a descriptive term implying a cerebellum with a reduced volume, but a normal shape and is stable over time. "Collectively, our study expands the spectrum of ANKRD17-related disorders to include cerebellar hypoplasia and bronchial dysplasia." (PMID 40604385, 2025).
hyperlipidemia (1 paper, 2023).
lung carcinoma (1 paper, 2023). "Still, given that ANKRD17 has been shown to induce JAK/STAT signaling pathways in a variety of cancers, and increased levels of ANKRD17 correlate with poorer prognosis in lung cancer patients, we considered it an interesting novel player." (PMID 37242727, 2023).
cancer (5 papers, 2021 to 2025). A tumor composed of atypical neoplastic, often pleomorphic cells that invade other tissues. "ANKRD17, a circular RNA, has been shown to promote cell growth, migration, and invasion in BC by regulating key molecules involved in cancer, such as certain micro-RNAs, primarily miR-143." (PMID 40136626, 2025). "Intriguingly, mutagenic transposition at the Ankrd17 gene locus, found exclusively in lung metastases, solicited our exploration of this gene in HCC-associated cancer spread." (PMID 40458187, 2025). "Moreover, several studies have identified the deregulation of Ankrd17 expression in various human cancers, including its role in bladder cancer metastasis." (PMID 40458187, 2025). "We used both in vitro and in vivo experiments to test this hypothesis and establish a connection between ANKRD17 and cancer aggressiveness." (PMID 40458187, 2025). "Interestingly, whilst the transcript level of certain genes shifted in a common direction across both clones, including ANKRD17 (down), BTC (up) and MTHFD2C (up), transcript level of the EREG gene, well characterised to be associated with numerous cancers, diverged between clones F and A5." (PMID 34432858, 2021). "Findings from the GSE6764 database revealed a common overexpression of both ANKRD17 and DDR1 in advanced stage HCC cases, particularly in patients with cancer that has spread to lymph nodes or other organs." (PMID 40458187, 2025).
infection (3 papers, 2020 to 2025). The state of being infected such as from the introduction of a foreign agent such as serum, vaccine, antigenic substance or organism. "The results showed, in both experiments (transfections and infections), a strong decrease in the ANKRD17 and Bif1 protein levels in MDBK cells expressing or containing miR-BF2-5p (mimic, U6-cassette, wt BFV infected)." (PMID 33147813, 2020).
tumor (2 papers, 2022 to 2025). "The Cancer Genome Atlas (TCGA) HCC database has documented significant overexpression of ANKRD17 in primary tumor samples, with recorded patient survival rates correlating with expression levels." (PMID 40458187, 2025). "The GEO DataSet GSE94016, which mimics tumor growth and metastasis in patient’s liver, was employed to assess the role of ANKRD17 and its impact on signaling pathways." (PMID 40458187, 2025). "Livers which showed overexpression of ANKRD17 revealed a more prominent liver to body weight ratio and heightened tumor burden compared to the control groups." (PMID 40458187, 2025). "ANKRD17-overexpressing cells and tumor samples revealed significantly higher expression of yes-associated protein 1 (Yap1), indicative of a dysregulated HIPPO signaling pathway, and notably elevated AKT phosphorylation at Ser473, an indicator of a dysregulated PTEN signaling pathway (respectively)." (PMID 40458187, 2025).
ANKRD17 also shares sentences with these, for which no sentence is quoted: autism (1 paper); autism spectrum disorder (1); bacterial infections (1); bladder cancer (1); Cyanosis (1); developmental delay (1); gastric cancer (1); gastritis (1); hemorrhage (1); hepatocellular carcinoma (1); transient tic disorder (1).